IL17A (interleukin 17A)
Diseases named in the same sentence as IL17A in open-access papers (continued):
Sharing a sentence is not in itself a finding about the gene and the disease.
psoriasis (continued). "More specifically, we identified PEDF, MDC and ANGPTL4 from the same pharmacodynamic pattern as IL-17A and KLK-7, for which the combined rate of decline between Week 4 and 16 could differentiate apremilast clinical responses in psoriasis." (PMID 31953524, 2020). "Imiquimod-induced psoriasis-like skin inflammation can be significantly attenuated by anti-IL-17A treatment, whereas this psoriasis model has no vascular dysfunction." (PMID 32587871, 2020). "Further underscoring their relevance in psoriasis pathogenesis, IL-17A genes were found to be upregulated in nonlesional psoriatic skin compared to healthy skin." (PMID 30909615, 2019). "Ingenuity canonical pathway screening identified the ‘role of IL-17A in psoriasis’ among the top ten most significant canonical pathways, when either lesional, or non-lesional protein expression was compared to healthy samples." (PMID 31388062, 2019). "In vivo neutralization of IL-17A is able to ameliorate EAU and IMQ-induced psoriasis." (PMID 31616442, 2019). "As the main source of IL-17A in the psoriasis mouse model is γδT cells, not Th17 cells, and IL-21 can inhibit the secretion of IL-17A in γδT cells, no alleviation of inflammation can be observed in IL-21R deficient mice." (PMID 31440249, 2019). "Moreover, IκBζ was identified as a critical regulator for Il17a expression in TH17 cells, suggesting that IκBζ promotes psoriasis via Il17a induction in T cells." (PMID 31622280, 2019). "Despite several monoclonal antibodies targeting IL-17A, IL-17F, or the IL-17RA being used as autoimmune disease treatment (i.e., psoriasis), their effect on blood pressure has not been established." (PMID 31186952, 2019). "We detected similar IL-17A levels in the blood of K14-IL17Aind Ctrl and KO mice, suggesting that differences in IL-17A overexpression were not responsible for the observed psoriasis resistance of the IκBζ-KO mice." (PMID 31622280, 2019). "Taken together, these results indicate that, although TIPE2-deficient T cells produced more IL-17A in both disease models, they are defective in migration to the skin in IMQ-induced psoriasis model but not to the eye in EAU model." (PMID 31616442, 2019). "IL-17A is not only secreted by CD4+ Th17 cells, but also by CD8+ T cells and certain cells of the innate immune system including neutrophilic granulocytes, thus further highlighting the tight connection of innate and adaptive immunity in psoriasis." (PMID 31402919, 2019). "Our data did not support the existence of a dual-secreting IL-17A/IL-22 Th17 cell as the major source of these cytokines in psoriasis." (PMID 31019502, 2019). "The mRNA levels of IL-17A, IL-22, IL-23, RORγt, and IFN-γ were increased in the lesional skin of psoriasis patients, whereas Foxp3, a vital transcriptional factor of Treg cells, was decreased in psoriasis patients." (PMID 31440249, 2019). "Taken together, these results do not support the current dogma that IL-17A/IL-22 dual-secreting Th17 T cells are the major driver of psoriasis pathophysiology." (PMID 31019502, 2019). "Some studies have shown decreased levels of IL-17A, TNF-α, S100A15, S100A7, S100A9 and IL-6 gene expression in PBMCs after NB-UVB treatment in patients with psoriasis whereas other pro-inflammatory mediators such as sVCAM-1, sICAM-1, sE-selectin, MMP-9, and MPO showed no significant reduction." (PMID 30865695, 2019). "RNA-seq data from NHK treated with TNF and rhodomyrtone confirmed the inhibitory effect of rhodomyrtone, particularly on the IL-17A/TNF induction of DEFB4, IL36G, and CXCL1, all known to be highly expressed in psoriasis lesions and investigated as potential biomarkers." (PMID 30321197, 2018). "While in our study the trend towards increased Treg-derived IL-17A in psoriasis was not statistically significant (p = 0.063 conventional plaque, p = 0.16 scalp, p = 0.15 palmoplantar), the relatively small number of patients in our study limited our power." (PMID 30054515, 2018).
psoriasis (continued). "Moreover, many molecularly targeted drugs for psoriasis and AD—TNF, IL-12/IL-23p40 subunit, IL-23p19 subunit, IL-17A, IL-17RA, and IL-4Rα—have been developed." (PMID 29642409, 2018). "IL-17A and/or IL-17F play important roles in many autoimmune diseases, e.g., leading to aggravation of such conditions as experimental autoimmune encephalomyelitis (EAE), psoriasis, rheumatoid arthritis (RA), and Crohn’s disease." (PMID 29892286, 2018). "Interestingly, adaptive T-cell-derived cytokines IL17A, IL17F, IL17C, IL26, IFNG, IL4, and IL10 show comparable levels in skin biopsies from paradoxical and classical psoriasis." (PMID 29295985, 2018). "As one of the most important cytokines in psoriasis, IL-17A increases IL-8 and MCP-1 production in a dose-dependent manner in human dermal fibroblasts (HDFs) both at protein and mRNA levels, and there exists synergistic activity between IL-17A and TNF-α." (PMID 28217129, 2017). "In an experimental model of psoriasis-like inflammation in mice using the TLR7-agonist imiquimod, dermal Vγ4+ γδ T cells persist in the skin and contribute to skin inflammation by producing IL-17A and IL-17F51,52." (PMID 27158469, 2016). "Subsequently, in a phase II study in patients with recalcitrant psoriasis, apremilast 20 mg BID led to decreases in proinflammatory gene expression in the lesional skin, including IL-8, IL-12/IL-23p40, IL-17A, and IL-23p19, as well as inducible nitric oxide synthase." (PMID 25973439, 2015). "Psoriasis-specific and non-specific DEGPs had distinct cytokine-response patterns, with only the former showing disproportionate induction by IL-17A in cultured keratinocytes." (PMID 26251673, 2015). "The IL-17A, IL-23, and TNF-α also revealed over-expression in this psoriasis-like skin model." (PMID 26355594, 2015). "Our study revealed increased IL-17A serum levels in Brazilian psoriasis patients in comparison with healthy controls, but no statistical correlation between this cytokine and PASI or age was found." (PMID 26351408, 2015). "Our study revealed increased IL-17A serum levels in psoriasis patients in comparison with healthy controls, but no statistical correlation between this cytokine and PASI or age was found." (PMID 26351408, 2015). "It has been reported that IL-17A has proangiogenic effects but in a HIF-1α-independent pathway; however, at the same time, IL-17A can stimulate the expression of proangiogenic factors in fibroblast and keratinocytes, including VEGF, feeding back the angiogenesis in psoriasis." (PMID 26136626, 2015). "Secukinumab (AIN457, a recombinant, highly selective, fully human IgG1 k mAb against IL-17A) was shown to improve clinical symptoms in patients with psoriasis, RA and noninfectious uveitis." (PMID 26062902, 2015). "Although our results do not show any correlation between serum levels of IL-17A, IL-22, and IL-6 and disease activity, the present study confirms that they were increased in Brazilian psoriasis patients in comparison to healthy volunteers." (PMID 26351408, 2015). "This unique aspect of IL-17A would have been overlooked by analyzing all PP-increased DEGPs in aggregate, without differentiating between psoriasis-specific and non-specific DEGPs." (PMID 26251673, 2015). "Moreover, IL-17A and OSM synergistically induced skin inflammation that recapitulated some features of psoriasis." (PMID 27095999, 2015). "Our findings thus uncover a new IL-17A signature, discernable at the transcriptome and proteome levels, which is prominent in psoriasis but attenuated or absent in other skin conditions." (PMID 26251673, 2015). "Moreover, IL-17A/IFN-γ or IL-17/IL-22 double-producing T cells have been described in the skin and blood of psoriasis patients." (PMID 26229971, 2015). "And interestingly, IL-17F expression increased more markedly than IL-17A in IMQ-treated mouse skin, indicating that IL-17F may have a greater contribution to IMQ-induced psoriasis-like inflammation." (PMID 23825622, 2013).
psoriasis (continued). "Notably, IL-9-induced secretion of IL-17A and increase in IL-17A+CD4+ T cell numbers was greater for psoriasis patients than for normal healthy controls." (PMID 23335955, 2013). "In addition, STAT1-57 genes were repressed in psoriasis lesions following treatment of patients with biologic agents, including anti-TNF therapy (P = 2.1×10−8; GSEA), anti-IL-17A therapy (P = 9.9×10−8; GSEA) and efalizumab (P = 4.5×10−12; GSEA)." (PMID 24260178, 2013). "Moreover, IL-9 significantly enhanced IL-17A production by cultured human peripheral blood mononuclear cells or CD4+ T cells, especially in psoriasis patients." (PMID 23335955, 2013). "Furthermore, a recent phase-II clinical study with a human antibody to IL-17A (AIN457, secukinumab) in psoriasis patients showed promising results supporting a role for Th17 in the pathophysiology of psoriasis." (PMID 23094018, 2012). "Furthermore, anti–IL-17A antibodies (such as AIN457) are currently being investigated for the clinical treatment of autoimmune diseases, including RA, psoriasis, and Crohn's disease, and therapeutic effects are starting to be reported." (PMID 22046434, 2011). "Psoriasis-specific cytokines (e.g., IL-12, IL-17A, IL-23) did not promote chemokine expression, but TNF-α – which could indicate both infection and sterile inflammation – was able to induce CCL-2 and CXCL10 expression." (PMID 41264606, 2025). "Furthermore, the lack of mPGES-1 increased the numbers of IL-17A-producing γδ T cells in the skin with IMQ-induced psoriasis, and γδ T-cell depletion resulted in a reduction of the facilitated psoriasis symptoms under the condition of mPGES-1 deficiency." (PMID 40481552, 2025). "Moreover, MOG drives Th17/Th1 cells to produce IL-17A and TNF-α, which may have a potential impact on psoriasis." (PMID 40564099, 2025). "While IL‐17A inhibitors have demonstrated efficacy in the treatment of psoriasis, they have not yet been explored in neurological autoimmunity beyond multiple sclerosis and may also warrant future investigation." (PMID 40781580, 2025). "Moreover, studies showed that bioactive IL-17A, rather than total IL-17A level, is a more suitable biomarker for monitoring disease activity in psoriasis patients." (PMID 40699767, 2025). "We observed that TNF-α-treated HaCaTs-derived exosomes can accelerate the psoriasis process by delivering AGAP2-AS1 to promote CD4+ T cell differentiation towards Th1 and Th17 cells and secretion of more inflammatory factors such as IFN-γ and IL-17A, which affect the immune microenvironment." (PMID 40520230, 2025). "Furthermore, an IL-17A-induced psoriasiform inflammation model in HaCaT keratinocytes demonstrated that XYJDY markedly suppressed AKR1B10 expression, reinforcing its candidacy as a pivotal therapeutic target in XYJDY-mediated treatment of psoriasis." (PMID 40735022, 2025). "This study aims to investigate the modulatory effects of IFN-γ and a proinflammatory cytokine mix (5MIX: IL-1α, IL-17A, IL-22, OsM, and TNF-α) on keratinocyte antigen-presenting capacities and their interactions with CD4+ lymphocytes, with a specific focus on their role in psoriasis pathogenesis." (PMID 39769151, 2024). "Additionally, IDG was shown to inhibit the expression of IL-6, IL-13, IL-17A, TNF-α, and MCP-1, suggesting that IDG may exert its therapeutic effects on psoriasis through its anti-inflammatory properties." (PMID 39465158, 2024). "Lastly, miR-125a-5p is also downregulated in psoriasis lesions; the methyltransferase EZH2 catalyzes the methylation of histone H3 at lysine 27, repressing transcription of miR-125a-5pn and eventually leading to increased expression of IL-17A-induced cytokines and cell proliferation." (PMID 38256115, 2024).
psoriasis (continued). "Despite the prominent clinicopathological features of psoriasis, including a shortened cell cycle and hyperproliferation of keratinocytes, research has focused predominantly on the role of tumor necrosis factor-α (TNF-α) and the IL-23/IL-17A axis in driving disease pathogenesis." (PMID 38446584, 2024). "IL-17A alone is insufficient for a substantial inflammatory response and may cooperate with other cytokines (such as TNF-α, IL-23, IL-1β, IL-6, and IL-22) to amplify the proinflammatory cascade characteristic of psoriasis." (PMID 38446584, 2024). "Peripheral blood mononuclear cells were acquired from 10 severe psoriasis patients and administrated by different concentrations of recombinant‐HMGB1 (rHMGB1) to detect the Th17 cell percentage, mRNA and protein levels of TLR4, IL‐23, IL‐17A and retinoid‐related orphan receptor γt (RORγt)." (PMID 38414294, 2024). "Anti-IL-17A mAb has the potential to disrupt the negative feedback loop of IL-17A in the hypothalamus and impact lipogenesis in surrounding adipose tissue, consequently affecting body weight in psoriasis patients." (PMID 38185620, 2024). "However, in pathological conditions of psoriasis, it is still unclear whether the HMGB1‐TLR4‐IL‐23‐IL‐17A pathway may be involved in and contribute to the IL‐17A aggregation and its inflammatory reaction." (PMID 38414294, 2024). "In addition, IL-17A, SOM, and IL-1α are major inflammatory factors contributing to psoriasis." (PMID 38607144, 2024). "This study aimed to investigate the effects of IFN-γ and a cytokine mix (5MIX: IL-1α, IL-17A, IL-22, OsM, and TNF-α) on the antigen-presenting capabilities of keratinocytes, with a specific focus on immune-mediated dermatological conditions such as psoriasis (Ps)." (PMID 39769151, 2024). "It is believed that IL17F may play a role in the development of psoriasis and psoriatic arthritis, but its effects are not as pronounced as those of IL17A." (PMID 37238999, 2023). "In psoriasis, MIR31HG was found to be elevated in psoriasis lesions and the upregulation of MIR31HG required IL-17A, IL-22, TNF-α, and IL-1α stimulation, demonstrating that nuclear factor kappa B inhibitor (NF-κB) signalling could be crucial crosstalk in psoriasis." (PMID 37636269, 2023). "The severity of psoriatic inflammation indicated by the Psoriasis Area and Severity Index (PASI) was positively correlated with S100A7 expression in the epidermis, which was downregulated during biological treatment with adalimumab, etanercept, ustekinumab, or a neutralizing antibody against IL-17A." (PMID 37891988, 2023). "In addition, the HA-ES group loaded with CUR showed relief of inflammatory symptoms according to the clinical psoriasis area and severity index (PASI), lower levels of TNF-α, IL-17A, IL-17F, IL-22, and IL-1β mRNA, and lower CCR6 protein expression compared to ES and PGS groups." (PMID 36678859, 2023). "Functionally, this mechanism resulted in the infiltration of pro‐inflammatory cytokines such as TNF‐α, IL‐1β, IL‐6, IL‐17A, and CXCL‐15, which enhances the inflammatory response in skin lesions and reinforces the cross‐talk between neutrophils and keratinocytes, ultimately aggravating psoriasis." (PMID 35281792, 2022). "However, none of the serum IL-17A, serum Claudin-1, and their combination was well-performed discriminating mild psoriasis from moderate-to-severe psoriasis with AUC of 0.553 (p = 0.5596), 0.518 (p = 0.8539), and 0.559 (p = 0.5225), respectively." (PMID 35340911, 2022). "Collectively, STFs might be the targets of IL-17A and TNF-α antagonists for psoriasis and AD." (PMID 35669784, 2022). "Moreover,skin-specific NLRP3 suppression can inhibit the proliferation and chemotaxis ofkeratinocytes through the downregulation of IL-1β, IL-23, IL-17A, C-X-Cmotif chemokine ligand 1 (CXCL1), as well as the improvement of Treg/Th17 ratio,thus ameliorating the skin lesions induced by psoriasis." (PMID 39076663, 2022).
psoriasis (continued). "The combinatorial biomarkers of serum IL-17A and Claudin-1 may serve as a good predictor for psoriasis, while they each or combined could not be candidate biomarkers assessing psoriasis severity." (PMID 35340911, 2022). "This study delineated that IκBζ may be a better target than TNFα or IL‐17A to manage psoriasis, as psoriasis‐like skin inflammation was still occurring in the absence of TNFα and IL‐17A, whereas it was completely missing in the absence of IκBζ." (PMID 36245291, 2022). "However, there are key differences that require further research for intervention; for example, anti-IL-17A is a highly effective psoriasis therapy but has been reported to have no impact on systemic CVD markers in psoriasis patients." (PMID 36477177, 2022). "Thus, data available to date (both molecular and functional) provide evidence on significantly impaired macrovascular endothelial function in psoriasis patients, possibly induced by the modulation of inflammatory responses (involving TNF-alpha, IL-17A) and increased levels of oxidative stress." (PMID 35883760, 2022). "However, splenectomy did not affect IMQ-induced psoriasis-like phenotypes compared with sham-operated mice, although splenectomy increased the expression of interleukin-17A mRNA in the skin of IMQ-treated mice." (PMID 36042262, 2022). "In addition to keratinocytes, dermal fibroblasts, through interaction with immune cells and cytokines such as IL-17A and TNF in psoriasis, can be a major source of IL-19 and IL-24 that contribute to perpetuation of psoriatic symptoms such as keratinocyte proliferation and acanthosis." (PMID 34616394, 2021). "Due to early discontinuation of the study, the PD effects of repeat dosing could not be assessed, and impact on endogenous serum level of IL-17A in psoriasis patients could not be further explored." (PMID 34040108, 2021). "Our results showed that PSORI-CM02 inhibited the phosphorylation of ERK1/2, p38, and JNK1 in IL-17A-stimulated HUVECs and in mice with IMQ-induced psoriasis, which suggests that the anti-angiogenic effects of PSORI-CM02 may be related to inhibition of the MAPK pathway." (PMID 33995368, 2021). "Consequently, we showed that the skin of IMQ-induced mice mimics the psoriatic characteristics with increased infiltration of inflammatory cells and increased levels of psoriasis-related cytokines and chemokines such as CXCL1, IL-25, IL-17A, IL-6, IL-1β, IL-36, CD4, and IFN-γ." (PMID 34641629, 2021). "Given that mice will not develop psoriatic dermatitis in the absence of external factors, the similar IL-17A expression levels among the three groups may be related to the lack of complete psoriasis-related immune pathways in mice." (PMID 34881280, 2021). "HaCaT cells represent an immortalized keratinocyte cell line and are considered as not very suitable for psoriasis research, because IL-17A or IFN-γ and TNF-α stimulation did not increase the expression of inflammatory markers (e.g., STAT3) or enhance cell proliferation in these cells." (PMID 33801280, 2021). "As epidermal hyperplasia and inflammation are hallmarks of psoriasis, our new findings indicate that alantolactone can not only alleviate these skin lesions by inhibiting inflammation but also relieve epidermal hyperplasia by reducing the expression of TNF-α, IL-6, IL-1β, IL-8, IL-17A, and IL-23." (PMID 34202301, 2021). "In addition, compared with the IMQ group, the protein expression of IL-17a (p = 0.008) and TNF-α (p = 0.016) in the back lesions decreased in the IMQ + TDG group on day 12, which are inflammatory factors involved in the pathogenesis of psoriasis." (PMID 33995034, 2021). "However, in previously unaffected non-lesional psoriasis skin, the IL-17A-generating potential of CD8+ CD103+ cells increases with disease duration." (PMID 34445713, 2021).